TRAJ30 (T cell receptor alpha joining 30)
Gene: T-cell receptor joining (J) gene on chromosome 14 (22,512,852 to 22,512,908, forward strand). Ensembl gene ENSG00000211859.
Diseases named in the same sentence as TRAJ30 in open-access papers:
TRAJ30 is named in the same sentence as 2 diseases in open-access papers, as found by Europe PMC text mining. Sharing a sentence is not in itself a finding about the gene and the disease. The quoted sentences say what the papers report.
COVID-19 (2 papers, 2021 to 2025). A disease caused by infection with severe acute respiratory syndrome coronavirus 2. "Nine out of the ten combinations that contributed most to the variability fell on the negative axis of PC1, and included TRAV9-2 × TRAJ30 and TRAV26-1 × TRAJ39, which both showed increased proportional usage in the COVID-19 CD4 repertoires compared to healthy controls." (PMID 40331338, 2025).
gastric cancer (1 paper, 2024). A primary or metastatic malignant neoplasm involving the stomach. "The paired CD103+ and CD103− T cell clones isolated from a patient with gastric cancer are characterized by the same T cell antigen receptor (TCR): TRAV8-6 TRAJ30, TRBV6-1 TRBJ2-7, recognizing the SSX-2 tumor antigen." (PMID 38561495, 2024).